TTBK2 (tau tubulin kinase 2)
Description:
Serine/threonine kinase that acts as a key regulator of ciliogenesis: controls the initiation of ciliogenesis by binding to the distal end of the basal body and promoting the removal of CCP110, which caps the mother centriole, leading to the recruitment of IFT proteins, which build the ciliary axoneme. Has some substrate preference for proteins that are already phosphorylated on a Tyr residue at the +2 position relative to the phosphorylation site. Able to phosphorylate tau on serines in vitro. Phosphorylates MPHOSPH9 which promotes its ubiquitination and proteasomal degradation, loss of MPHOSPH9 facilitates the removal of the CP110-CEP97 complex (a negative regulator of ciliogenesis) from the mother centrioles, promoting the initiation of ciliogenesis. Required for recruitment of CPLANE2 and INTU to the mother centriole (By similarity).
Synonyms: KIAA0847; SCA11; TTBK
Tractability: Small molecule: a structure with a bound ligand is known; a high-quality ligand is known; it belongs to a druggable protein family. PROTAC: ubiquitination databases record sites on it; a small molecule that binds it is known.
Target class: Enzyme; Kinase; Protein Kinase; CK1 protein kinase group
Chemical probes: TTBK1-IN-1 (high quality)
Gene: Protein-coding gene on chromosome 15 (42,738,730 to 42,920,850, reverse strand). Ensembl gene ENSG00000128881.
Subcellular location: Cell projection, cilium; Cytoplasm, cytoskeleton, cilium basal body; Cytoplasm, cytoskeleton, microtubule organizing center, centrosome, centriole; Cytoplasm, cytosol; Nucleus
Subcellular location (Human Protein Atlas): Cytosol; Microtubules; Basal body; Primary cilium; Primary cilium transition zone
Pathways (Reactome):
Organelle biogenesis and maintenance: Anchoring of the basal body to the plasma membrane
Gene Ontology:
Molecular function: kinesin binding; protein binding; protein serine kinase activity; protein serine/threonine kinase activity; microtubule plus-end binding; tau protein binding; tau-protein kinase activity; ATP binding; protein kinase activity
Biological process: cilium assembly; microtubule cytoskeleton organization; negative regulation of microtubule depolymerization; negative regulation of protein localization to microtubule; peptidyl-serine phosphorylation; regulation of cell migration; cerebellar granular layer development; cerebellar granule cell precursor tangential migration; cerebellum development; smoothened signaling pathway
Cellular component: centriole; ciliary transition zone; cytosol; extracellular region; nucleus; ciliary basal body; ciliary base; cilium; microtubule cytoskeleton
Genetic constraint (gnomAD): Loss-of-function variants: 27 observed, 114.24 expected, observed/expected ratio (o/e) 0.24, 90% interval 0.17 to 0.33. The upper end of that interval is the gene's LOEUF score, 0.33, which puts it in group 1 of 6, group 1 being the genes least tolerant of losing a copy. Missense variants: 1,359 observed, 1,569.5 expected, observed/expected ratio (o/e) 0.87, 90% interval 0.83 to 0.91. Synonymous variants: 531 observed, 556.22 expected, observed/expected ratio (o/e) 0.95, 90% interval 0.89 to 1.03.
Homologues: Orthologues: macaque TTBK2 (99% identical), chimpanzee TTBK2 (94% identical), dog TTBK2 (94% identical), rabbit TTBK2 (93% identical), pig TTBK2 (91% identical), rat Ttbk2 (90% identical), mouse Ttbk2 (90% identical), guinea pig TTBK2 (86% identical), tropical clawed frog ttbk2 (66% identical), Drosophila melanogaster Asator (31% identical), Caenorhabditis elegans ttbk-7 (20% identical), Caenorhabditis elegans C56C10.6 (11% identical), and 60 more. Paralogues in human: TTBK1 (39% identical), CSNK1D (11% identical), CSNK1E (11% identical), CSNK1G3 (11% identical), CSNK1G2 (10% identical), CSNK1G1 (10% identical), CSNK1A1 (9% identical), CSNK1A1L (9% identical), VRK2 (9% identical), VRK1 (8% identical), CDC7 (6% identical), VRK3 (5% identical).
Diseases named in the same sentence as TTBK2 in open-access papers:
TTBK2 is named in the same sentence as 43 diseases in open-access papers, as found by Europe PMC text mining. Sharing a sentence is not in itself a finding about the gene and the disease. The quoted sentences say what the papers report.
glioma (34 papers, 2017 to 2024). A benign or malignant brain and spinal cord tumor that arises from glial cells (astrocytes, oligodendrocytes, ependymal cells). "In glioma, the circular RNA Tau tubulin kinase 2 (Circ-TTBK2) promotes cell proliferation and invasion while inhibiting ferroptosis by sponging miR-761 and activating Integrin Subunit Beta 8 (ITGB8)." (PMID 39595619, 2024). "Another study revealed that circ-TTBK2, also named has_circ_0000594, regulates glioma cell proliferation, invasion, and ferroptosis through the miR-761/ITGB8 axis." (PMID 37332354, 2023). "Knockdown of circ-TTBK2 or increased expression of miR-761 was found to delay the proliferation and invasion of glioma cells and promote ferroptosis." (PMID 37332354, 2023). "TTBK2, NAV1, and CTTNBP2 were considered as protective factors, while SRCIN1, TRIO, KIF18A, and SLAIN2 were risk factors for glioma." (PMID 36979179, 2023). "TTBK2 was found to modulate the cell proliferation and invasion in glioma cell lines via miR-520b/EZH2 axis." (PMID 35685372, 2022). "Attenuated TTBK2 expression inhibited the proliferation, migration and invasion of Glioma cells via modulating miR-1283 and CHD1." (PMID 35685372, 2022). "For example, circNDUFB2 was identified as a tumor suppressor in non-small cell lung cancer, while circ-TTBK2 exerted an oncogenic role in glioma." (PMID 35436983, 2022). "Circ-ZNF264, circPCMTD1, and circ-TTBK2 promote cell proliferation, migration and invasion in glioma cell lines by regulating their miRNAs." (PMID 33816552, 2021). "Circular RNA TTBK2 modulates ferroptosis, invasion, and proliferation of glioma cells by miR-761/ITGB8 signaling." (PMID 34520391, 2021). "And circ-TTBK2 regulates the proliferation, migration, and invasion of glioma cells by targeting miR-217." (PMID 30621721, 2019). "The expression of circ-TTBK2 is increased in glioma tissues, which promotes cell proliferation, migration, and invasion but inhibits apoptosis." (PMID 30064463, 2018). "In glioma, both circ-TTBK2 and cZNF292 are highly expressed and play crucial oncogenic roles in promoting glioma malignancy progression." (PMID 30126353, 2018). "Herein, the expression and function of circular RNA circ-TTBK2 were investigated in human glioma cells." (PMID 28219405, 2017). "Circ-TTBK2 was located in the cytoplasm and was significantly upregulated in glioma tissues compared with normal brain tissues." (PMID 28219405, 2017). "Stable circ-TTBK2 overexpression and inhibition in glioma cells were established to investigate the role of circ-TTBK2." (PMID 28219405, 2017). "CircRNA circ-TTBK2 was significantly upregulated in glioma tissues and cell lines and acted as a miR-217 sponge." (PMID 29349062, 2017). "The proliferation of glioma cells in the circ-TTBK2 (+)+miR-217 (−) group was significantly increased than that in the circ-TTBK2 (+)+miR-217 (+) group." (PMID 28219405, 2017). "Mechanistically, PI3K/AKT and ERK pathways were involved in circ-TTBK2 regulated malignant progression of glioma cells." (PMID 28219405, 2017). "In summary, our study revealed that circ-TTBK2 inhibition restrained malignant progression of glioma cells by upregulating miR-217." (PMID 28219405, 2017). "MiR-217 expression was negatively correlated with the pathological grades of glioma, and similarly with circ-TTBK2, miR-217 was also located in the cytoplasm." (PMID 28219405, 2017). "Moreover, TTBK2, NAV1, and CTTNBP2 were protective factors for glioma, while SRCIN1, TRIO, KIF18A, and SLAIN2 were risk factors." (PMID 36979179, 2023). "Moreover, it was reported that the circRNA TTBK2 was upregulated in glioma tissues and cells and inhibited ferroptosis via the miR-761/ITGB8 axis to promote glioma proliferation and invasion." (PMID 35342359, 2022). "Additionally, restoration of miR-217 dramatically reversed the stimulation of glioma growth by circ-TTBK2." (PMID 35883576, 2022). "miR-520b/EZH2 mediates circular RNA TTBK2-accelerated glioma." (PMID 33758783, 2021).
glioma (continued). "For instance, circ-TTBK2 and circPCMTD1 act as sponges of miR-224-5p to promote glioma progression." (PMID 33816552, 2021). "In addition, the expression levels of circZNF292 and TTBK2 gene-derived circRNAs in gliomas are downregulated and upregulated, respectively." (PMID 30064463, 2018). "It was shown that circ-TTBK2 is up-regulated in glioma and cell lines, such as U87 and U251." (PMID 30583549, 2018). "In this study, we demonstrated that circ-TTBK2 was upregulated in glioma tissues and cell lines." (PMID 28219405, 2017). "We next aimed to investigate whether HNF1β was involved in the circ-TTBK2-mediated regulation of glioma cell progression." (PMID 28219405, 2017). "More importantly, inhibition of circ-TTBK2/miR-217/HNF1β/Derlin-1 axis may be a potential therapeutic target for human gliomas." (PMID 28219405, 2017). "Moreover, overexpressed circ-TTBK2 hindered apoptosis of glioma cells compared with the circ-TTBK2 (+)-NC group." (PMID 28219405, 2017). "Moreover, reintroduction of miR-217 significantly reversed circ-TTBK2-mediated promotion of glioma progression." (PMID 28219405, 2017). "Overexpression of circ-TTBK2 promoted glioma cells malignant progression." (PMID 28219405, 2017). "Moreover, qRT-PCR and western blot were used to determine the expressions of HNF1β mRNA and protein in glioma cells treated with circ-TTBK2 inhibition and/or miR-217 overexpression." (PMID 28219405, 2017). "Circ-TTBK2 plays an oncogenic role in glioma cells by acting as a miR-217 sponge." (PMID 29096676, 2017). "Having confirmed that miR-217 expression was negatively regulated by circ-TTBK2 expression, we further investigated whether miR-217 reversed circ-TTBK2-mediated promotion of glioma cells progression." (PMID 28219405, 2017). "We further investigated whether circ-TTBK2 exerted oncogenic function in glioma through regulating miR-217 and found that the restoration of miR-217 robustly reversed the circ-TTBK2-induced promotion of glioma cell malignant progression." (PMID 28219405, 2017). "Circ-TTBK2 expression was significantly increased in glioma tissues and cells." (PMID 28219405, 2017). "And the expression of circ-TTBK2 was positively correlated with the pathological grades of glioma." (PMID 28219405, 2017). "By sequestering miR-217 activity, circ-TTBK2 enabled higher expression of oncogenic proteins HNF1β and Derlin-1, which promoted cell proliferation, migration, and invasion, while inhibiting apoptosis of glioma cells." (PMID 29349062, 2017). "Besides, our preliminary experiment demonstrated that TTBK2 circular RNA (circ-TTBK2, also named has_circ_0000594 according to circBase) was upregulated in glioma tissues." (PMID 28219405, 2017). "Due to our preliminary result, circ-TTBK2 expression was upregulated in glioma tissues." (PMID 28219405, 2017). "Moreover, glioma cells treated with circ-TTBK2 (−)+miR-217 (+) exhibited higher ratio of apoptosis compared with cells treated with circ-TTBK2 (−)+miR-217 (−)." (PMID 28219405, 2017). "Transwell assay was used to measure whether circ-TTBK2 dysregulation could affect the migration and invasion of glioma cells." (PMID 28219405, 2017). "Circ-TTBK2 harbors MREs for miR-217, which has a tumor-suppressive role in glioma cells." (PMID 29147648, 2017). "Inhibition of the circ-TTBK2/miR-217/HNF1/Derlin-1 axis may be a viable target for human gliomas." (PMID 35883576, 2022). "Similarly, circ-TTBK2 was upregulated in glioma tissues and cells." (PMID 35006436, 2020). "Further study found that circ-TTBK2 was a sponge of miR-761 to modulate ITGB8, and knockdown of circ-TTBK2 induced lipid ROS production, which promoted ferroptosis and retarded cell proliferation, invasion in glioma cells, suggesting a potential biomarker for clinical glioma treatment." (PMID 35006436, 2020). "This indicated that circ-TTBK2 might sponge to miR-217 to modulate its function in glioma cell." (PMID 28219405, 2017).
glioma (continued). "Therefore, we hypothesized that dysregulation of circ-TTBK2 was involved in the regulation of glioma malignancy." (PMID 28219405, 2017). "Therefore, circ-TTBK2 might be involved in the modulation of glioma cell biological behavior and exerted critical function in glioma progression." (PMID 28219405, 2017). "Moreover, enhanced circ-TTBK2 facilitated malignant progression of glioma cells." (PMID 28219405, 2017). "However, the function of miR-217 in glioma and circ-TTBK2/miR-217 functional network in modulating glioma malignant behavior remains unknown." (PMID 28219405, 2017). "Compared with the normal samples, except for SLAIN2, the CTTNBP2, KIF18A, NAV1, and TRIO protein expression in glioma was elevated, while SRCIN1 and TTBK2 were decreased." (PMID 36979179, 2023). "Our study found that compared with normal tissues, CTTNBP2, KIF18A, NAV1, SLAIN2, and TRIO were upregulated in glioma, while SRCIN1 and TTBK2 were downregulated." (PMID 36979179, 2023). "In gliomas, circ-TTBK2 has been activated by cavernous miR-761 and subsequent ITGB8 and inhibited IRC-TTBK2 to promote derastin-induced ferroptosis." (PMID 36187333, 2022). "Circ-TTBK2 uses sponge miR-761 to target ITGB8 to regulate the proliferation, invasion, and ferroptosis of glioma cells, providing a promising biomarker for the clinical treatment of human glioma." (PMID 35688814, 2022). "Levels of circRNA TTBK2 and integrin subunit β 8 (ITGB8) are upregulated in glioma tissues and cells with downregulated miRNA-761 levels, and circRNA TTBK2 regulates cell proliferation, invasion, and ferroptosis via the miRNA-761/ITGB8 axis." (PMID 33868986, 2021). "Multiple circRNAs, such as circ-TTBK2, circ-ABCB10 and circ_0001730, have demonstrated to play a crucial role in glioma via acting as competitive endogenous RNAs (ceRNAs)." (PMID 34727925, 2021). "To date, several circRNAs have been reported to play crucial roles in gliomas, such as circ-SMARCA5, circ-MMP9, circ-NT5E, circ-TTBK2, and circ-LINC-PINT." (PMID 31905344, 2020). "Circ-TTBK2 regulated the miR-217/HNF1b/Derlin-1 pathway to promote the progression of glioma; and circ-SHKBP1 regulated the angiogenesis of U87 glioma-exposed endothelial cells through miR-544a/FOXP1 and miR-379/FOXP2 pathways." (PMID 31179240, 2019). "In fact, circ-TTBK2 and miR-217 interact with each other in an AGO2-dependent manner and upregulation of circ-TTBK2 induced the malignant behavior of glioma cells via downregulation of miR-217." (PMID 29147648, 2017). "For instance, RNA circ-TTBK2 is overregulated in glioma tissues and cell lines, while linear TTBK2 does not change its level." (PMID 35846075, 2022). "Circular TTBK2 expression was increased in glioma tissues and cell lines, whereas linear TTBK2 expression was not altered in glioma tissues or cells." (PMID 35883576, 2022). "In glioma, circ-TTBK2 enhanced cell proliferation and invasion and inhibited ferroptosis via sponging miR-761 and subsequent ITGB8 activation, knockdown of circ-TTBK2 promoted erastin-induced ferroptosis." (PMID 32709863, 2020). "In contrast, however, it has been reported that circ-TTBK2 RNA is upregulated in glioma tissues and cell lines, while linear TTBK2 RNA is not dysregulated." (PMID 28937658, 2017). "We found that circ-TTBK2 was upregulated in glioma tissues and cell lines, while linear TTBK2 was not dysregulated in glioma tissues and cells." (PMID 28219405, 2017). "Remarkably, TTBK2 mRNA expression was not changed in glioma tissues and cells." (PMID 28219405, 2017). "The expression of circ-TTBK2 but not linear TTBK2 was elevated in glioma tissues." (PMID 29096676, 2017). "Circ-TTBK2, but not linear TTBK2, exerted oncogenic role in glioma cells." (PMID 28219405, 2017). "However, linear TTBK2 expression was not changed in glioma tissues and cells." (PMID 28219405, 2017).
spinocerebellar ataxia type 11 (15 papers, 2014 to 2025). Spinocerebellar ataxia type 11 (SCA11) is a subtype of autosomal dominant cerebellar ataxia type III (ADCA type III) characterized by the early-onset of cerebellar signs, eye movement abnormalities and pyramidal signs. "Recently reported TTBK1 inhibitors target not only TTBK1 but also TTBK2, which loss of function mutation is known to lead to spinocerebellar ataxia 11 due to the similarity of catalytic domains between these two tau-kinases." (PMID 37853497, 2023). "Mutations in the gene encoding tau tubulin kinase-2, TTBK2, cause spinocerebellar ataxia, type 11 (SCA11)." (PMID 33228809, 2020). "The Spinocerebellar ataxia type 11-associated mutation of the serine/threonine kinase Tau tubulin kinase 2 dominantly interferes with ciliogenesis and cilium stability." (PMID 31920562, 2019). "Mutations in TTBK2 have been shown to cause spinocerebellar ataxia type 11 (SCA11), a progressive neurodegenerative disorder characterized by tau pathology." (PMID 25473830, 2014). "Variants in the gene coding for TTBK1 are associated with Alzheimer's disease, while mutation in TTBK2 causes spinocerebellar ataxia 11 (SCA11), both of which are characterized by pathologic alterations of tau." (PMID 25473830, 2014). "TTBK2 is ubiquitously expressed in multiple tissues and genetically linked to spinocerebellar ataxia type 11." (PMID 24808823, 2014). "Thus, dysfunctional TTBK2 causes spinocerebellar ataxia type 11, and mutations of DNAH14 cause neurodevelopmental deficits." (PMID 40019676, 2025). "Mutations in the closely related gene TTBK2 cause spinocerebellar ataxia, type 11." (PMID 33228809, 2020). "In addition to the critical requirement for TTBK2 in ciliogenesis, particular dominant mutations that disrupt TTBK2 cause a hereditary ataxia, spinocerebellar ataxia type 11 (SCA11)." (PMID 30532139, 2018). "Mutations in TTBK2, which yield a mutant protein truncated after the N-terminal kinase domain, cause spinocerebellar ataxia type 11 (SCA11): a rare neurodegenerative disease of which symptoms include pronunciation difficulties, involuntary eye movement and ataxia." (PMID 26969328, 2016). "Mutations of TTBK2 are associated with spinocerebellar ataxia type 11." (PMID 25950000, 2015). "Truncating variants in TTBK2 gene cause spinocerebellar ataxia type 11 (SCA11), a rare form of autosomal dominant cerebellar ataxia." (PMID 41422144, 2025). "We previously showed that Tau tubulin kinase 2 (TTBK2), a kinase causally mutated in the hereditary neurodegenerative disorder spinocerebellar ataxia type 11 (SCA11), is an essential regulator of ciliogenesis." (PMID 31934864, 2020). "As TTBK2 is essential for initiating cilia assembly, it is not surprising that a pathogenic mutation of TTBK2 leads to a neurological disorder known as spinocerebellar ataxia 11 (SCA11), characterized by atrophy of the Purkinje cells of the cerebellum." (PMID 38523660, 2024). "Tau tubulin kinase 2 (TTBK2) is a critical regulator of ciliogenesis, and is also mutated in a hereditary neurodegenerative disorder, spinocerebellar ataxia type 11 (SCA11)." (PMID 31934864, 2020).